SLC25A25 (solute carrier family 25 member 25)
Description:
Electroneutral antiporter that most probably mediates the transport of adenyl nucleotides through the inner mitochondrial membrane (By similarity). Has calcium-dependent ATP-magnesium/inorganic phosphate antiporter activity. Could also have a broader specificity for adenyl nucleotides (By similarity). By regulating the mitochondrial matrix adenyl nucleotide pool, could adapt to changing cellular energetic demands and indirectly regulate adenyl nucleotide-dependent metabolic pathways (By similarity). Acts downstream of Ca(2+)-permeable cation channel PKD2/TRPP2 and it is likely that PKD2-mediated Ca(2+) signaling activates SLC25A25 antiporter activity (By similarity). Required for left-right pattern specification (By similarity).
Synonyms: SCaMC-2; KIAA1896; SCAMC2; PCSCL; MCSC
Tractability: Antibody: UniProt predicts a signal peptide or a membrane-spanning region. PROTAC: ubiquitination databases record sites on it; its protein half-life has been measured.
Gene: Protein-coding gene on chromosome 9 (128,068,169 to 128,109,245, forward strand). Ensembl gene ENSG00000148339.
Subcellular location: Mitochondrion inner membrane
Subcellular location (Human Protein Atlas): Mitochondria; Vesicles
Gene Ontology:
Molecular function: ATP:phosphate antiporter activity; calcium ion binding
Biological process: ATP transport; transmembrane transport
Cellular component: mitochondrion; mitochondrial inner membrane
Genetic constraint (gnomAD): Loss-of-function variants: 32 observed, 56.27 expected, observed/expected ratio (o/e) 0.57, 90% interval 0.43 to 0.76. The upper end of that interval is the gene's LOEUF score, 0.76, which puts it in group 3 of 6, group 1 being the genes least tolerant of losing a copy. Missense variants: 548 observed, 667.89 expected, observed/expected ratio (o/e) 0.82, 90% interval 0.76 to 0.88. Synonymous variants: 304 observed, 273.15 expected, observed/expected ratio (o/e) 1.11, 90% interval 1.01 to 1.22.
Homologues: Orthologues: chimpanzee SLC25A25 (99% identical), macaque SLC25A25 (99% identical), rat Slc25a25 (96% identical), guinea pig SLC25A25 (90% identical), tropical clawed frog slc25a25 (85% identical), pig SLC25A25 (84% identical), rabbit SLC25A25 (83% identical), mouse Slc25a25 (80% identical), zebrafish slc25a25b (79% identical), zebrafish slc25a25a (64% identical), zebrafish slc25a24l (32% identical). Paralogues in human: SLC25A23 (61% identical), SLC25A24 (56% identical), SLC25A41 (36% identical), SLC25A12 (22% identical), SLC25A13 (22% identical), SLC25A42 (16% identical), SLC25A39 (16% identical), SLC25A29 (16% identical), SLC25A16 (15% identical), SLC25A6 (15% identical), SLC25A19 (15% identical), SLC25A28 (15% identical), and 37 more.
Diseases named in the same sentence as SLC25A25 in open-access papers:
SLC25A25 is named in the same sentence as 31 diseases in open-access papers, as found by Europe PMC text mining. Sharing a sentence is not in itself a finding about the gene and the disease. The quoted sentences say what the papers report.
asthma (3 papers, 2019 to 2022). "Discovered DMRs annotated to genes implicated in allergy and asthma, Th2 activation and eosinophilia (EPX, IL4, IL13, PRG2, CLC and ZFMP1) and genes previously associated with asthma and IgE in an EWAS of blood (ACOT7, SLC25A25)." (PMID 35344303, 2022). "Discovered DMRs annotated to genes implicated in allergic asthma, Th2 activation and eosinophilia (EPX, IL4, IL13) and genes previously associated with asthma and IgE in EWAS of blood (ACOT7, SLC25A25)." (PMID 31300640, 2019).
acute myeloid leukemia (1 paper, 2022). Acute myeloid leukemia (AML) is a group of neoplasms arising from precursor cells committed to the myeloid cell-line differentiation. "In contrast, the expression of SLC25A4, SLC25A8, SLC25A12, and SLC25A25 was associated with better prognosis of patients in acute myeloid leukemia." (PMID 36254139, 2022).
bladder urothelial carcinoma (1 paper, 2022). "Only SLC25A25 was lowly expressed in bladder urothelial carcinoma." (PMID 36254139, 2022).
breast carcinoma (1 paper, 2022). "It was found that the mutation rate of SLC25A25 was the highest in breast cancer cell lines and SLC25A24 had a higher mutation level in colorectal cancer cell lines." (PMID 36254139, 2022). "Moreover, the mutation analysis of SLC25 family in tumor cell lines revealed that the mutation rate of SLC25A25 was the highest in breast cancer, suggesting that SLC25A25 was more apt to mutate in the environment of breast tissue." (PMID 36254139, 2022).
breast invasive carcinoma (1 paper, 2022). "Besides, SLC25A25 was reduced in not only kidney renal papillary cell carcinoma but also breast invasive carcinoma." (PMID 36254139, 2022).
cervical squamous cell carcinoma (1 paper, 2022). A squamous cell carcinoma arising from the cervical epithelium. "SLC25A25 mutation was associated with poor prognosis in cervical squamous cell carcinoma and adenocarcinoma, cholangiocarcinoma, and ovarian serous cystadenocarcinoma." (PMID 36254139, 2022).
endometrial carcinoma (1 paper, 2022). A malignant tumor arising from the epithelium that lines the cavity of the uterine body. "SLC25A7 and SLC25A25 were reduced in uterine Corpus Endometrial Carcinoma." (PMID 36254139, 2022).
glioma (1 paper, 2024). A benign or malignant brain and spinal cord tumor that arises from glial cells (astrocytes, oligodendrocytes, ependymal cells). "Given its high abundance in the mitochondria of brain tissue and in glioma cells, it will also be interesting to investigate its role in this tissue, particularly whether SLC25A25 deficiency influences neuronal fitness." (PMID 37984987, 2024).
hepatocellular carcinoma (1 paper, 2022). A malignant tumor that arises from hepatocytes. "SLC25A24 was upregulated in hepatocellular carcinoma while SLC25A25 was downregulated." (PMID 36254139, 2022).
hypospadias (1 paper, 2022). Hypospadias is the displacement of the urethral meatus on the ventrum of the penis. "Likewise, SLC25A25 expression was found to be mis-regulated in fulminant type I diabetes, HCCs and hypospadias." (PMID 34687432, 2022).
lung adenocarcinoma (1 paper, 2022). A carcinoma that arises from the lung and is characterized by the presence of malignant glandular epithelial cells. "In lung adenocarcinoma, SLC25A7 and SLC25A25 had decreased expression while SLC25A41 was elevated." (PMID 36254139, 2022).
lung squamous cell carcinoma (1 paper, 2022). "In lung squamous cell carcinoma, SLC25A27 and SLC25A25 were reduced." (PMID 36254139, 2022).
ovarian serous cystadenocarcinoma (1 paper, 2022). A malignant serous cystic epithelial neoplasm arising from the ovary. "Besides, the mutation of many SLC25s made high-risk effects on the prognosis of ovarian serous cystadenocarcinoma such as SLC25A8, SLC25A24, SLC25A25, and SLC25A31." (PMID 36254139, 2022).
thyroid cancer (1 paper, 2022). "In thyroid cancer, significant downregulation was observed in SLC25A7 and SLC25A25." (PMID 36254139, 2022).
uterine corpus endometrial carcinoma (1 paper, 2022). A endometrial carcinoma (disease) that involves the body of uterus. "Almost all SLC25s had high mutation frequency in uterine corpus endometrial carcinoma, including SLC25A12, SLC25A13, SLC25A14, SLC25A23, SLC25A24, and SLC25A25." (PMID 36254139, 2022). "In uterine corpus endometrial carcinoma, the mutation of SLC25A4, SLC25A25, and SLC25A27 had certain impacts on their expression." (PMID 36254139, 2022).
cancer (1 paper, 2022). A tumor composed of atypical neoplastic, often pleomorphic cells that invade other tissues. "Additionally, SLC25A25 was significantly downregulated in 10 of 33 types of cancer tissue." (PMID 36254139, 2022).
SLC25A25 also shares sentences with these, for which no sentence is quoted: eosinophilia (2 papers); adenocarcinoma (1); allergic asthma (1); atherosclerosis (1); cholangiocarcinoma (1); colorectal cancer (1); Hypertension (1); Hypoglycemia (1); influenza (1); kidney stones (1); melanoma (1); neuroblastoma (1); Parkinson disease (1); tumor (1); vitiligo (1).